ACSL6 (acyl-CoA synthetase long chain family member 6)
Diseases named in the same sentence as ACSL6 in open-access papers (continued):
Sharing a sentence is not in itself a finding about the gene and the disease.
cancer (24 papers, 2016 to 2025). A tumor composed of atypical neoplastic, often pleomorphic cells that invade other tissues. "ACSL6 is involved in lipid metabolism, expressed in the brain, thyroid, and breast tissues, and is associated with diverse types of cancer." (PMID 35756649, 2022). "Although ACSL6 has also been suggested to play a role in cancer; research on this topic remains limited." (PMID 41288931, 2025). "Remarkably, ACSL6 expression is typically diminished in various cancer types, yet it is notably elevated in CRC, where its overexpression is linked to increased cellular proliferation and elevated levels of glycolytic products." (PMID 40041860, 2025). "The overexpression of ACSL6 in our tumor cohort agrees with an ACSL6 downregulation in most forms of cancers, except CRC." (PMID 31434359, 2019). "Regarding ACSL6, its role in cancer is less frequently documented." (PMID 40932861, 2025). "In addition to ACSL1, ACSL4, and ACSL5, ACSL3 and ACSL6 also contribute to cancer progression, with their roles to be further elaborated in the context of specific cancers." (PMID 41288931, 2025). "Within this subclone that may have emerged in response to treatment, mutations were also detected within the genes AKAP9 and ACSL6, both of which are listed in the COSMIC cancer gene census." (PMID 37081523, 2023). "The data available for ACSL6 suggest that this isoenzyme has opposite roles in different cancers." (PMID 31344914, 2019). "ACSL6 has been acknowledged for its substantial effect on FA metabolism in the brain and its involvement in facilitating spermatogenesis, and similar mechanisms is noteworthy for broadening our understanding of its effect in the control of cancer, particularly with respect to LCRS." (PMID 39206814, 2024). "In addition, downregulation of ACSL6 has been found in most carcinoma, except in CRC." (PMID 36160009, 2022). "Among these, PEBP1/STK11 co-expression strongly negatively correlates in all cancer types with enzymes that increase the biosynthesis of fatty acids such as members of the ACSL family (ACSL1, ACSL3, ACSL4, ACSL5, and ACSL6)." (PMID 40806276, 2025). "Except that, we also found ACSL6, a member of the long-chain acyl-CoA synthetase family, was found to be decreased in GBM, which has been observed in many forms of cancers, except in CRC, but the mechanisms still need to be clarified." (PMID 36838582, 2023). "Based on function, the 12 FRGs can be grouped into four classes: Lipid metabolism (GPX4, LPCAT3, ACSL5, and ACSL6), antioxidant metabolism (CD44, SESN2, and AIFM2), iron metabolism (CISD1 and HSPB1), and cancer metabolism (SOCS1, FH, and G3BP1)." (PMID 34784264, 2022). "The 12 FRGs are divided into 4 categories according to their functions: lipid metabolism (GPX4, LPCAT3, ACSL5, ACSL6), antioxidant (CD44, SESN2, AIFM2), iron metabolism (CISD1, HSPB1), and cancer metabolism (SOCS1, FH, G3BP1)." (PMID 35559049, 2022). "We found only 4 significant results in this analysis: First, low ACSL3 expression in Naïve B cells, and low ACSL5 and ACSL6 in Naïve CD8 cells, correlated with worse patient survival outcomes, demonstrating a potential reliance on these for an effective anti‐cancer immune response." (PMID 39853696, 2025). "Several ACSLs-related reviews have summarized the mechanisms and function of the ACSLs in cancer: ACSL1 and ACSL3 may lead to cancer progression and worse prognosis, while ASCL5 and ACSL6 act as key suppressor with the opposite effect." (PMID 36507355, 2022). "Validation of the whole-body mouse knockout of some isoenzymes such as ACSL3, ACSL5 and ACSL6 does not result in lethality or any overt dysfunction which renders them cancer cell specific vulnerabilities." (PMID 31344914, 2019). "ACSL6, PRPS1 and PRPS2 genes represent potential therapeutic targets to limit cancer cell growth using specific inhibitors, which could re-program cancer cell metabolism by reducing FA." (PMID 31434359, 2019).
cancer (continued). "Potential off‐target sites that are not gRNA‐based but related to cancer genes were Metazoa‐SRP, RARA, and ACSL6 found in HLA‐A11R hESCs, and PLCG1 found in iC9‐HLA‐A11R hESCs." (PMID 37199039, 2023).
tumor (8 papers, 2016 to 2025). "Blocking of ACSL6 impairs the tumor growth and upregulates FLI1, which reduces the levels of COLs and compromises irradiation‐induced autophagy, leading to considerable therapeutic benefits during radiotherapy." (PMID 39206814, 2024). "ACSL6 in tumour cells mainly promotes the anabolism of fatty acids to provide energy, but its specific function in infiltrating immune cells in the TME still requires further exploration." (PMID 38045683, 2023). "On the contrary, ACSL6 downregulation significantly correlates with poor patient survival and acts as a tumor suppressor in AML, which is consistent with our findings." (PMID 34784264, 2022). "Based on these results, we concluded that ACSL6 is preferentially expressed in tumor tissues, and its expression is greatly upregulated by IR, and inferred that ACSL6 may play an important role in the radiological response of LC." (PMID 39206814, 2024). "Results showed that some of the most relevant pathway’s regulators and effectors (CD36, FABP4, PLIN1, PLIN4, SCD5 and ACSL6) showed significantly lower expression in tumor tissue samples (p.adjusted < 0.01, data not shown)." (PMID 40860798, 2025).
infection (2 papers, 2016 to 2021). The state of being infected such as from the introduction of a foreign agent such as serum, vaccine, antigenic substance or organism. "In the present study, we analyzed different time points of infection and found that ACSL1, ACSL3, ACSL4, ACSL5 and ACSL6 were all recruited into the lumen of the Ct inclusion as early as 6 hpi and as late as 24 hpi." (PMID 26988341, 2016).
neurological diseases (2 papers, 2021 to 2025). "Thus, the loss of ACSL6 function or availability of its preferred substrate DHA over aging could contribute to age-induced neurological diseases and disorders." (PMID 34100386, 2021). "Concurrently, the unique binding affinity of ACSL6 for DHA confers distinctive importance in elucidating the pathological mechanisms of neurological disorders and developing potential therapeutic interventions." (PMID 41288931, 2025). "Given the critical role of the ACSL family in polyunsaturated fatty acid metabolism, it likely plays a significant role in neurological disorders, particularly ACSL6." (PMID 41288931, 2025).
hematologic diseases (1 paper, 2024). "Multiple chromosomal rearrangements involving ETV6 (such as ETV6::RUNX1, ETV6::ABL1, ETV6::NTRK3, and ETV6::ACSL6) have been demonstrated to play a crucial role in the development of several hematologic diseases such as AML, as well as in their diagnosis and prognosis." (PMID 39723366, 2024).
neurodegenerative disease (1 paper, 2021). A disorder of the central nervous system characterized by gradual and progressive loss of neural tissue and neurologic function. "ACSL6 is downregulated in or has identified single nucleotide polymorphisms associated with age-related neurodegenerative diseases." (PMID 34100386, 2021).
ACSL6 also shares sentences with these, for which no sentence is quoted: acute lymphoblastic leukemia (1 paper); Anxiety (1); chronic eosinophilic leukemia (1); chronic myeloid leukemia (1); colon adenocarcinoma (1); COVID-19 (1); dementia (1); eosinophilia (1); hematologic neoplasms (1); liver cancer (1); metabolic disorders (1); myelodysplastic syndrome (1); myeloma (1); myeloproliferative disorder (1); myeloproliferative neoplasm (1); Parkinson disease (1); periampullary adenocarcinoma (1); polycythemia vera (1); refractory anemia (1); retinal degeneration (1); steatosis (1).